SOX2 (SRY-box transcription factor 2)
Diseases named in the same sentence as SOX2 in open-access papers (continued):
Sharing a sentence is not in itself a finding about the gene and the disease.
cancer (continued). "OCT-4, Nanog, and SOX-2 are known to be expressed only in specific human cancer types." (PMID 35151264, 2022). "Inhibition of SOX2 expression was reported to attenuate cancer cell proliferation." (PMID 35190631, 2022). "The formation of this complex promotes the translation of the oncogene mRNA, causing cancer cells to acquire increased malignant tumor-forming capacity in vivo and increased protein levels of pluripotency factors OCT4, SOX2, NANOG and KLF4 (Kruppel-like factor 4)." (PMID 35954194, 2022). "Additionally, studies found that SOX2 regulates the stem cell properties and drug resistance of cancer cells, which was consistent with our previous findings for the role of SOX2 in NSCLC A549/CDDP cells published on Chinese journal." (PMID 35059870, 2022). "IPSs can be derived from mature cells, or even cancer cells, by forcibly expressing stem cell markers such as Oct4 (octamer-binding transcription factor 4), Sox2 (sex determining region Y-box 2), Myc (Myelocytomatosis proteins), and Klf4 (Krüppel like factor 4)." (PMID 35371349, 2022). "Moreover, ZEB1 has been associated with the development of the cancer stem cell (CSC) phenotype through the regulation of miRNAs controlling the expression of stemness transcription factors such as SOX2 and KLF4." (PMID 35682554, 2022). "In addition, SOX2 regulates the epithelial-mesenchymal transition (EMT) of various cancer types through Wnt signaling, and it has been reported that BCAT1 can induce the EMT process in LC cells." (PMID 36119495, 2022). "In addition, MPC1 deficiency significantly increased cancer stem cell markers such as Nanog homeobox (NANOG), octamer-binding transcription factor 4 (OCT4), and SRY-box transcription factor 2 (SOX2) in LUAD cells in vivo." (PMID 34059057, 2021). "Increased NANOG and SOX2 stemness gene expression in cancer cells treated with CAF-conditioned media may lead to greater cisplatin resistance." (PMID 34760886, 2021). "Transcription factor genes (OCT4, KLF4, SOX2, MYC, NANOG, and REX1) and cell surface markers (CD133, LGR5), which are associated with embryonic stem cells, induced pluripotent stem cells, and cancer stem cells, have been selected for measuring expression levels from the selected tissues." (PMID 34452555, 2021). "Many reports have suggested that SOX-2 plays an important role in cancer and cancer stem cells." (PMID 34885925, 2021). "Furthermore, LR004-VC-MMAE treatment also significantly reduced the expression of various cancer stemness marker genes, including Oct4, Sox2, KLF4 and EpCAM." (PMID 34879870, 2021). "SOX2 is another transcription factor that contributes to normal and cancer stem cell self-renewal." (PMID 33499351, 2021). "Since chemoresistance is associated with cancer cell stemness, we tested some stem cell transcription factors and found that Oct4A was particularly upregulated by ABCG1 overexpression, whereas c-Myc and SOX2 were upregulated by both ECM1a and ABCG1." (PMID 34244494, 2021). "Overexpression of SOX2 has been detected in human cancers, and therefore, it may serve as an oncogene." (PMID 33789601, 2021). "Treatment resistance of lethal tumors was linked to OCT4, SOX2, and NANOG in cancer patients." (PMID 34452555, 2021). "Moreover, pimavanserin also impaired the expression of several Gli1 downstream cancer stem cell markers, including Oct-4, SOX2 and NANOG, and suppressed the size and number of PANC1 tumorspheres." (PMID 34439102, 2021). "The expressions of cancer stem cell-related genes, Sox2 and Oct4, were decreased by siRNA of YAP1." (PMID 34445421, 2021). "Taken together, these data suggest a stronger role for SOX2 in chemotherapy resistance, a central feature of TICs that may contribute to cancer recurrence." (PMID 33445692, 2021).
cancer (continued). "Sox2 maintains stemness of cancer cells by regulating the Hippo pathway." (PMID 34774083, 2021). "SOX2 as a critical transcriptional regulator is amplified in various cancer types and affects cancer cell physiology via involvement in complicated cell signaling and protein-protein interactions, including triggering cell apoptosis by the combined effects of ROS overproduction." (PMID 34187410, 2021). "We analyzed these proteins because (i) SOX2’s proliferative function in cancer cells is exerted, at least in part, through direct repression of p21CIP1 and p27KIP1 expression; (ii) there is an interaction between SOX2 and p27KIP1 in mice, in which we have just demonstrated that Srr2 plays a role." (PMID 33805518, 2021). "Deregulation of SOX2 expression is an important agent promoting the pathogenesis of cancer." (PMID 35008527, 2021). "In contrast, PKCλ/ι has a pro-carcinogenic effect by phosphorylating and activating SOX2, an effect that may be more relevant in 3q26-amplified cancers." (PMID 34436017, 2021). "However, our data highlight the pronounced heterogeneity of BTK protein expression in distinct cell types including cancer stem-like cells (SOX2), TAMs (CD163) and microglia (CD68)." (PMID 34645618, 2021). "Furthermore, there is growing evidence that cancer stemness is associated with the expression of OCT3/4, SOX2, c-MYC, and other genes involved in the self-renewal regulation of malignant cancer cells, as well as normal stem cells." (PMID 34440702, 2021). "Collectively, these data suggest that these two cancer types may selectively amplify lineage-specific regulatory elements together with the SOX2 oncogene." (PMID 34880227, 2021). "Oct4 and Sox2 can drive the expression of lncRNAs in cancer cells and ESCs." (PMID 33628268, 2021). "Sox2, a transcription factor involved in the regulation of embryonic development, functions as a novel regulator of cell invasion, migration, and metastasis in several cancer types." (PMID 34504430, 2021). "Indeed, chemoresistant cancer cells, often characterized by high levels of SOX2, are commonly more prone to exploit the oxidative metabolism." (PMID 34768751, 2021). "The expression of SRY-box transcription factor 2 (SOX2) is altered in multiple types of human malignancies, where increases in SOX2 via different pathways can result in metastasis, drug resistance, and the proliferation of cancer cells." (PMID 34831420, 2021). "Several factors known to play a central role in embryonic stem cells and used in epigenetic reprogramming, such as pluripotency factors OCT4, NANOG, SOX2 and Klf4, have been reported to be expressed in subpopulations of cancer cells from different tumour types." (PMID 33453053, 2021). "Moreover, SFRP2 overexpression reduced the expression levels of cancer stemness markers such as Oct4, Lin28, Nanog, and Sox2." (PMID 34852024, 2021). "These putative cancer stem cells have unlimited self-renewal governed by a variety of embryonic transcription factors, including octamer-binding transcription factor 4 (Oct-4), sex-determining region Y-box 2 (Sox-2), and Nanog." (PMID 34903921, 2021). "Indeed, our findings experimentally demonstrate the relevance of SRR2 as an enhancer of SOX2 expression in cancer cells because deletion of SRR2 in GBM cells leads to a reduction of SOX2 expression." (PMID 33805518, 2021). "Together, these data suggest that the TMPRSS4/TWIST1–SLUG/SOX2 axis could be exploited as a target for anti-cancer therapy." (PMID 34809669, 2021). "In addition, the expression of cancer stemness markers (Oct4, Lin28, Nanog, and Sox2) was obviously increased in SW1783 and SW1088 cells after SFRP2 knockdown." (PMID 34852024, 2021). "Additionally, when IGF-1 function was blocked by miR-28-5p, the expressions of cancer stemness-related genes SOX2, OCT4, and NANOG were repressed." (PMID 33669204, 2021). "Nonetheless, little research has focused on SOX2 expression and its clinical value in cancer." (PMID 33789601, 2021).
cancer (continued). "The downregulation of SPN in breast cancer cell lines increases the tumorigenic properties and cancer stem cell properties, such as the formation of tumorspheres and the expression of stem cell genes (NANOG, OCT4, SOX2 and KLF4), whereas the overexpression of SPN causes the opposite effect 17,18." (PMID 33537097, 2021). "In addition, analysis of the Cancer Cell 2010 dataset showed that TMPRSS4 expression was significantly correlated with expression of SOX2 (rho = 0.484, P = 3.48e-10) and TWIST1 (rho = 0.368, P = 3.491e-06)." (PMID 34809669, 2021). "The YB1 transcription factor induces the stemness-related gene expression and epithelial-mesenchymal transition in hepatocellular carcinoma while YY1 is associated with transcription factor (SOX2, OCT4, BMI1) expression in cancers suggesting a co-regulatory role in cancer stem cells." (PMID 33453053, 2021). "The customized development of iPeps derived from oncogenic TFs that are overexpressed in aggressive and chemoresistant carcinomas, such as SOX2, can selectively target specific tumors overexpressing these TFs thereby sensitizing these chemoresistant carcinomas to chemotherapy drugs." (PMID 34502261, 2021). "In conclusion, we report that an FGFR/AKT/SOX2 signaling axis controls cancer stemness in PDAC and may therefore represent a potential therapeutic target in the fight against this very aggressive form of cancer." (PMID 32457900, 2020). "Moreover, SOX2 levels influence cell fate decisions and are crucial determining factors in the proliferation of both normal and cancer cells." (PMID 32098209, 2020). "Third, protein interaction networks of unique DEGs of the two voles relabeled that among the severe hypoxia-specific DEGs in L. mandarinus, the most prominent core genes were RLN3, AVP, CALCA, and SOX2, which regulate responses to stress, metabolism, and cancer." (PMID 32256671, 2020). "Additionally, SOX2 involves in the migration, invasion, and proliferation of cancer cells and resistance to therapy." (PMID 32104175, 2020). "However, PI3K inhibitors including A66 and BEZ235 are observed to increase the expression of cancer stem cell (CSC) genes (SOX2, OCT4 and MSI1) in GBM CSC models, which exhibit therapy resistance." (PMID 32333246, 2020). "SOX-2 is consistently overexpressed in all cancer cells relative to fibroblast cells." (PMID 32111825, 2020). "It has been reported that the use of radiation to destroy cancer cells after surgery may convert differentiated cancer cells to CSCs through the expression of CSC markers such as Oct4/Sox2/KLF4." (PMID 32426267, 2020). "The role of OCT4 in human cancers is much less studied than SOX2." (PMID 32093282, 2020). "In addition, SOX2 also exerts a critical effect on paclitaxel‐ and gemcitabine‐induced drug resistance in several cancers." (PMID 32596945, 2020). "The up‐regulation of SOX2, SOX4, SOX5, SOX8, SOX9 and SOX18 are found to be associated with poor outcome in different cancer types; however, the up‐regulation of SOX11 and SOX30 is favourable for the prognosis in other cancer types." (PMID 32363730, 2020). "The SOX2-Hippo regulatory circuit remained conserved in multiple SOX2-dependent cancers like GBMs." (PMID 30517668, 2020). "As an oncoprotein, SOX2 expression confers cancer cells resistance to apoptosis." (PMID 32728033, 2020). "The GLI family maintains CSCs in various cancers (e.g., glioblastoma, non-small cell lung cancer, chronic myeloid leukemia, and colon cancer) via the regulation of various target genes that are associated with CSC maintenance, including SOX2, NANOG, and BMI1." (PMID 32859041, 2020). "Since Sox2 expression in cancer has been linked to CSC activity, it raised the question of whether the Sox2-positive cells, particularly the Sox2hi cells, in the CAF-CM-treated sublines are CSCs." (PMID 33228022, 2020). "Our finding of cancer-specific SNPs in exosomal SOX2 DNA sequence may reflect those changes in the cancer stem cells as well as cancer cells." (PMID 32092088, 2020).
cancer (continued). "In pancreatic cancers, SOX2+ PDAC cells could gain cancer stem-like pluripotent potentials through partial EMT phenotypes: upregulation of EMT master regulators (e.g. SNAIL, SLUG, and TWIST), and downregulation of epithelial markers (e.g. E-cadherin and ZO1)." (PMID 30517668, 2020). "Furthermore, kynurenine increased the tumorsphere formation capability and the expression of cancer stemness genes including Oct4 and Sox2." (PMID 32545442, 2020). "This evidence extends our knowledge with regard to the diverse roles of SOX2 and HIFs in cancers." (PMID 32913192, 2020). "LncRNA SOX2-OT (Sox2 overlapping transcript) has been identified as an oncogene in various cancers." (PMID 32848755, 2020). "Although various EGFR inhibitors are currently under clinical use, it is unknown how much its anti-cancer activity is attributable to SOX2 depletion." (PMID 31748974, 2020). "Whether stemness-related SOX2 regulates cancer stemness and vasculature needs to be explored further." (PMID 32144236, 2020). "The TF SOX2 acted as a key regulator in biological processes, such as transcriptional regulation, cell proliferation, and oncogenesis, and the differential expression of SOX2 has been confirmed in various cancers." (PMID 32598517, 2020). "SOX2 is another marker of cancer cell stemness in multiple cancer types." (PMID 32210076, 2020). "Sox2 was shown to be a master regulator for cancer stem cells in skin SCC27." (PMID 32358507, 2020). "In majority of cancers, SOX2 expression had been predominantly identified in the absence of genetic amplifications and might depend upon yet unknown upstream regulatory mechanisms." (PMID 30517668, 2020). "Despite its active involvements in self-renewal and maintenance of stemness of embryonic- and neuronal stem cells (SCs), reprogramming somatic cells into induced pluripotent stem cells (iPSCs), and in regenerative medicine; recent studies have demonstrated the oncogenic roles of SOX2 in cancers." (PMID 30517668, 2020). "Importantly, down-regulation in SOX2 levels has been reported to significantly decrease cell viability, growth, sphere formation, and tumorigenicity in multiple cancer types." (PMID 32457900, 2020). "SOX2 involves in the development and maintenance of stem-like properties in cancer cells." (PMID 32104175, 2020). "SOX2 may also contribute toward the initiation of CSCs in cancers and it is found to be the most upregulated transcription factor in squamous cell carcinoma." (PMID 32092088, 2020). "At the same time, this axis may offer a molecular mechanism for therapeutic intervention in SOX2+ cancers and, more specifically, against SOX2+ CSCs." (PMID 32664542, 2020). "SOX2 regulates the self-renewal and pluripotency of undifferentiated stem cells such as human embryonic stem cells and plays an important role in maintaining the stem cell–like features in cancer cells." (PMID 32104175, 2020). "Neither was SOX2 expression associated with cancer-specific survival for stage II (HR = 0.83; 95%CI 0.40–1.69; p = 0.600) nor stage III disease (HR = 0.91; 95%CI 0.59–1.40; p = 0.670)." (PMID 32365581, 2020). "Indeed, SOX2 overexpression or amplification is often observed in many different types of human cancers, which, importantly, is correlated with poor survival of cancer patients." (PMID 32728033, 2020). "Up until now, it has been proved that SOX2 acts as a tumor propagator in a variety of cancers." (PMID 33152990, 2020). "In addition, it is well established that SOX2 regulates cellular proliferation in many cancer types; for instance, its overexpression in the lungs of mice induces rapid proliferation and, in some cases, leads to adenocarcinomas." (PMID 32093282, 2020). "The additional SNPs found with varying degrees in the sequences representing the rest of the SOX2 gene, in control as well as cancer exosomes, warrant a detailed analysis that can predict the effects of amino acid substitutions on translation and the protein functions." (PMID 32092088, 2020).
cancer (continued). "Our data suggest that betavulgarin, which targets Sox2/Stat3 signaling, might be used as an anti-cancer agent." (PMID 32630026, 2020). "Sox2 has been connected to stemness in embryonal development and in cancer." (PMID 33228022, 2020). "In addition, studies have highlighted the central roles of Wnt/β-catenin in the EMT and stemness maintenance processes, which occur via regulation of SOX2 in cancer cells." (PMID 33153498, 2020). "It is unknown, however, how much of the anti-cancer activity of these indirect approaches can be attributable to SOX2 depletion." (PMID 32191225, 2020). "Given the roles of SOX2 in cancer biology and CSCs, it is of high importance to investigate the downstream regulatory pathways either directly or indirectly mediated by SOX2 and the development of specific SOX2-targeting cancer therapies." (PMID 32754274, 2020). "We demonstrate that an FGFR/AKT/SOX2 axis controls cancer stemness in PDAC and therefore may represent an important therapeutic target in the fight against this very aggressive form of cancer." (PMID 32457900, 2020). "Furthermore, the qPCR analysis also found that a cancer‐related miRNA, hsa‐miR‐340‐5p, which showed a higher binding affinity with SOX2 under miRanda analysis, was markedly downregulated in SOX2‐ overexpression cells." (PMID 32130794, 2020). "These evidences support SOX2 as a prospective biomarker for cancer stemness in this sense that even if there were numerous CSC markers, such as cell surface marker CD15 (stage-specific embryonic antigen 1), very few of them had been demonstrated to actively promote stem-like properties." (PMID 30517668, 2020). "Given that a key mechanism of drug resistance relates to the incapacity of most standard therapeutics to eradicate the minor subpopulation of CSC with self-renewal and seeding capacity, SOX2 has been suggested as an attractive anti-cancer target to prevent CSC-mediated clinical relapse." (PMID 32191225, 2020). "Because 4SC-202 affects the cell population(s) that express CD133, FOXM1, and SOX2 and there is strong evidence that these proteins are cancer stem cell markers, our data suggest that 4SC-202 may decrease the cancer stem-like cell population." (PMID 32210076, 2020). "Some genes, which appeared to be virtually switched off in B4GALNT2-expressing cells, are involved in the basic properties of cancer cells, such as stemness (SOX2, ROR1), epithelial to mesenchymal transition (EMT) (NID1, ALX1), and growth (FAM110B, PEG10, MID2)." (PMID 32290493, 2020). "Accordingly, certain CSC bio-behaviors can be defined as rare therapy-resistant, self-renewing cancer cells that aberrantly express SOX2, which might provide specificity for CSC-targeted drug screening." (PMID 32191225, 2020). "Thus, SOX2 is, in general, an oncogenic protein to promote human tumorigenesis, and a validated cancer drug target." (PMID 32728033, 2020). "Moreover, cancer stem cell markers like SOX2 and OCT4 and related levels of microRNAs are believed to be potential biomarkers for predicting carcinogenicity resulting from exposure to PM2.5." (PMID 32098209, 2020). "AKT inhibitor can effectively downregulate SOX2 and suppress cancer stemness." (PMID 32457900, 2020). "In addition, TGF-β can activate the signaling pathways such as PD-1 and Sox2 to ensure the growth and survival of cancer cells." (PMID 32752069, 2020). "Sox2 is a poorly druggable transcription factor, but targeting signaling molecules upstream or downstream of Sox2 (Sox2 inducers and Sox2 targets, respectively) is under investigation in some human cancers." (PMID 33553286, 2020). "This again re-enforces our conclusion that SOX2 is a key regulator of cancer stemness in PDAC." (PMID 32457900, 2020). "CD133 and SOX2 are largely utilized as cancer stem cell markers in GSCs." (PMID 32410622, 2020).